RN7SL792P (RNA, 7SL, cytoplasmic 792, pseudogene)
Gene: Miscellaneous RNA gene on chromosome 17 (15,408,384 to 15,408,688, forward strand). Ensembl gene ENSG00000239888.
Homologues: Orthologues: chimpanzee Metazoa_SRP (98% identical), macaque Metazoa_SRP (91% identical). Paralogues in human: RN7SL2 (83% identical), RN7SL1 (82% identical), RN7SL3 (80% identical), RN7SL296P (79% identical), RN7SL300P (79% identical), RN7SL786P (78% identical), RN7SL88P (78% identical), RN7SL126P (78% identical), RN7SL147P (78% identical), RN7SL357P (78% identical), RN7SL444P (78% identical), RN7SL589P (78% identical), and 699 more.